IL21 (interleukin 21)
Diseases named in the same sentence as IL21 in open-access papers (continued):
Sharing a sentence is not in itself a finding about the gene and the disease.
lupus (continued). "Additionally, GSEA also revealed an association with immunologic signature terms, including “GSE10325 CD4 T-cell vs lupus CD4 T-cell up”, “GSE19198 1 h vs 24 h IL21 treated T-cell up”, “GSE15930 naïve vs 24 h in vitro stim CD8 T-cell down”, “GSE18893 tconv vs treg 24 h TNF stim up”, etc.." (PMID 37161020, 2023). "Moreover, the importance of the interaction between BCL-6 and IL-21 in Tfh cell differentiation and autoantibody production should not be ignored, especially in lupus and some autoimmune diseases." (PMID 35637283, 2022). "In this study, we present new evidence of the importance of PRL in the development of SLE by increasing the absolute number of TFH cells, the activation of TFH cells, and IL21 secretion in lupus-prone mice." (PMID 33763492, 2021). "And then there are the potent TPH cells with TFH like phenotype but are CXCR5-; they help lupus B cells also by producing IL-21; and IL-10–producing CCR6+T cells populate lymph nodes of SLE patients." (PMID 33936042, 2021). "Indeed, Ig class-switch recombination (CSR), during T and B cell cognate interaction, which is Th1 IFNγ cytokine dependent in lupus, may occur before the TFH IL-21 driven expansion of autoantibody producing B cells in germinal center, which comes later." (PMID 33936042, 2021). "Besides IL-21, IFN-γ also contributes to lupus in both human and murine models." (PMID 31057553, 2019). "In addition, it has been shown that a distinct subset of TFH cells coexpressing IFN-γ and IL-21 drives inflammatory bowel disease, and has been recently described in lupus albeit not in the brain." (PMID 29593732, 2018). "Moreover, hyper Th17 response (with increased IL-17/IL-21 producing CD4+ T cells) is not observed in all of the lupus-prone mice." (PMID 30013031, 2018). "Notably, although anti-IL-21 also attenuated disease in other lupus-prone mouse models, Act1 levels were not reduced in those lupus mice, indicating that IL-21 is probably modulated by multiple pathways." (PMID 30013031, 2018). "For example, in vivo data show that blockade of IL-21 signaling using an IL-21 receptor Fc fusion protein (IL-21R Fc) decreases the disease severity in several murine models including collagen-induced arthritis, the MRL-Faslpr lupus model and the diabetic NOD model." (PMID 23496892, 2013). "For instance, overexpression of IL-21 induces inflammation; in the BXSB.6-Yaa+/J mouse model of systemic lupus erythematosus (SLE), affected mice exhibit elevated levels of IL-21, whereas IL-21R−/−BXSB.6-YAA+/J mice do not develop SLE." (PMID 40943537, 2025). "Third, basophil depletion dramatically dampened both constitutive and PMA-ionomycin-induced IL-21 and IL-4 productions by TFH cells only in the lupus-like context, without significantly influencing their IFNγ or IL-17A production abilities." (PMID 38649353, 2024).
rheumatoid arthritis (102 papers, 2007 to 2026). A chronic, systemic autoimmune disorder characterized by inflammation in the synovial membranes and articular surfaces. "A study showed that a 480 kb block on chromosome 4q27 encompassing the KIAA1109/Tenr/IL-2/IL-21 gene cluster is associated with rheumatoid arthritis." (PMID 37667381, 2023). "In conclusion, IL-21 plasma levels are increased in patients with rheumatoid arthritis associated with disease severity." (PMID 33673829, 2021). "Interleukin-21 (IL-21) has been associated with systemic diseases like rheumatoid arthritis and Crohn's disease that follow a chronic inflammatory cascade." (PMID 26998377, 2016). "Recently IL-21 has gained importance as it has been associated with the pathogenesis of inflammatory breakdown in various systemic diseases like rheumatoid arthritis, colitis, and inflammatory bowel disease." (PMID 26998377, 2016). "Evidence shows association of IL-21 with various systemic conditions such as coronary artery disease, rheumatoid arthritis, and inflammatory bowel disease." (PMID 26998377, 2016). "Since periodontitis and rheumatoid arthritis were previously associated with one another this systematic review was aimed to evaluate the expression of IL-21 in periodontitis." (PMID 26998377, 2016). "The IL-21/IL-21R axis is a proinflammatory cytokine complex that has been associated with chronic inflammatory diseases including rheumatoid arthritis and inflammatory bowel disease." (PMID 24757284, 2014). "A candidate gene approach, in a large case–control association study in the Dutch population, has shown that a 480 kb block on chromosome 4q27 encompassing KIAA1109/Tenr/IL2/IL21 genes is associated with rheumatoid arthritis." (PMID 19302705, 2009). "Using a family-based study, we have provided a trend for the association of the KIAA1109/Tenr/IL2/IL21 gene region with rheumatoid arthritis in populations of European descent." (PMID 19302705, 2009). "IL-21 has also been associated with different autoimmune and inflammatory diseases, such as rheumatoid arthritis and inflammatory bowel disease." (PMID 17982568, 2007). "To test whether common genetic variants in the IL-21 gene are associated with predisposition to rheumatoid arthritis development, we genotyped rs907715, rs2221903 rs2055979 polymorphism in 211 RA patients and 303 healthy controls." (PMID 33673829, 2021). "Moreover, the KIAA1109/Tenr/IL2/IL21 locus was also earlier associated with another immunological disorder, namely rheumatoid arthritis." (PMID 26941931, 2015). "Continued study of inflammatory pathways should identify potential targets for the specific and effective treatment of inflammatory and other chronic diseases, just as blocking IL-21 is effective in controlling rheumatoid arthritis." (PMID 41463030, 2025). "Pathogenic Th17 cell, as a special Th17 cell subset, triggered and aggravated the immune response of chronic inflammatory diseases, such as periodontitis, IBD, and rheumatoid arthritis, through IL-17, IL-21, IL-22, IL-23, and GM-CSF (gene: CSF2)." (PMID 41318555, 2025). "In rheumatoid arthritis, IL-21 impairs pro-inflammatory activity of M1-like Mφ, but promotes M2 polarization of Mφ." (PMID 37628738, 2023). "IL-21 has been shown to activate the JAK/STAT pathway in peripheral immune cells in several disease contexts including rheumatoid arthritis and lymphoma." (PMID 35624463, 2022). "IL-21 can promote cell proliferation and differentiation in tumors and inflammatory diseases, such as intestinal chronic diseases, type I diabetes, and rheumatoid arthritis." (PMID 35774604, 2022). "IL-21 plays an important role in the pathogenesis of various inflammatory systemic diseases such as inflammatory bowel disease, rheumatoid arthritis and colitis." (PMID 36013509, 2022). "Further, IL-21 levels are positively correlated with disease activity scores in rheumatoid arthritis patients." (PMID 33673829, 2021).
rheumatoid arthritis (continued). "The plasma level of IL-21 was significantly higher in subjects with rheumatoid arthritis relative to healthy controls (p < 0.0001)." (PMID 33673829, 2021). "In 2017, a new subset of IL‐21‐producing memory CD4+ helper T cells was shown to be strongly expanded in the synovial fluid of seropositive rheumatoid arthritis patients." (PMID 32697399, 2020). "In other diseases mediated by immune system imbalance, such as rheumatoid arthritis, hepatitis B, and nephrotic syndrome, the amount of IL-21 in peripheral blood is also increased." (PMID 32855360, 2020). "Overproduction of IL-21 occurs in many inflammatory diseases such as rheumatoid arthritis, psoriasis and SLE, and is reported to be an important pro-inflammatory cytokine in animal transplant models." (PMID 31024571, 2019). "Periodontitis is a chronic inflammatory condition which shows increased local and systemic levels of inflammatory mediators and markers of inflammation like IL-21, and a direct link has been established between periodontitis and rheumatoid arthritis." (PMID 26998377, 2016). "BRD2 directly regulates multiple TH17-associated cytokines, including IL17, IL21, and GMCSF32, and altered TH17 cells mediate autoimmune conditions, including multiple sclerosis, psoriasis, rheumatoid arthritis, and CD32." (PMID 28008999, 2016). "Niu, X.; He, D.; Zhang, X.; Yue, T.; Li, N.; Zhang, J.Z.; Dong, C.; Chen, G. IL-21 regulates Th17 cells in rheumatoid arthritis." (PMID 31557991, 2016). "Among the proinflammatory cytokines, IL-17A, IL-21 and IL-23 are considered as those which play crucial roles in the induction of local inflammation and cartilage destruction diseases such as rheumatoid arthritis (RA)." (PMID 27820818, 2016). "Specific targeting of IL-6 using tocilizumab therapy in patients with rheumatoid arthritis led to a significant reduction in circulating Tfh cell numbers and IL-21 production, which was correlated with reduced plasmablast formation." (PMID 25681343, 2015). "It has been known for some years that IL-17 and cytokines involved in the production of Th17 lymphocytes, among other IL-23 and IL-21, have an important role in the pathogenesis of rheumatoid arthritis." (PMID 25510225, 2014). "For some years now, IL-17 and cytokines involved in Th17 lymphocyte production, including IL-23 and IL-21, have been believed to play a significant role in the pathogenesis of rheumatoid arthritis." (PMID 25510225, 2014). "Since relatively little is known about the Tfh cells in rheumatoid arthritis (RA) patients, in this study, Tfh-cell frequency, related cytokine IL-21, and transcription factor Bcl-6 were investigated in 53 patients with RA and 31 health controls." (PMID 22649468, 2012). "In an animal model of rheumatoid arthritis, blocking the IL-21 pathway by administration of a fusion protein (IL-21R.Fc) ameliorated disease severity." (PMID 21959034, 2011). "In rheumatoid arthritis, high plasma IL-21 levels connect to greater disease activity." (PMID 41127878, 2025). "Therefore, while directly blocking IL-21 is still being studied, inhibiting it signalling pathways presents a hopeful treatment option for rheumatoid arthritis." (PMID 41127878, 2025). "There is another randomized, double-blind, placebo-controlled study that aims to neutralize IL-21 cytokines using a recombinant α(IL)-21 monoclonal antibody for the treatment of rheumatoid arthritis, but so far only safety endpoints and pharmacokinetics were assessed." (PMID 36293075, 2022). "Additionally, B. longum RAPO significantly inhibited Th17 cells and Th17-related genes—IL-17A, IRF4, RORC, IL-21, and IL-23R—in the PBMCs of rheumatoid arthritis patients." (PMID 34867956, 2021). "The role of IL-21 in the pathogenesis of rheumatoid arthritis is well investigated." (PMID 33673829, 2021). "IL-21 plays a crucial function in rheumatoid arthritis pathogenesis." (PMID 33673829, 2021).
rheumatoid arthritis (continued). "The importance of IL-21 in has also been demonstrated in murine models of rheumatoid arthritis." (PMID 30233580, 2018). "IL-21 could stimulate the expression of TNF-α in fibroblasts as it was shown in T cells during Rheumatoid arthritis." (PMID 26772733, 2016). "Given their capacity to produce a variety of cytokines (IL4, IL21 and IFNγ), their association with ACPA positive RA and their presence in the synovium, we suggest an important role of double positive T cells in the pathogenesis of rheumatoid arthritis." (PMID 24667579, 2014). "Furthermore, in vivo blockade of IL-21 ameliorated disease progression and severity in some of these settings, as well as in animal models of rheumatoid arthritis and Sjogren’s syndrome." (PMID 24600453, 2014). "Indeed, in addition to Type 1 diabetes, lymphopenia is characteristic of several human diseases that also exhibit increased levels of IL-21, such as rheumatoid arthritis, Crohn's disease, SLE, and Sjogren's syndrome." (PMID 18773086, 2008). "Moreover, it has been described that in patients with rheumatoid arthritis Tph lymphocytes are able to release, in addition to IL-21, Th1-type pro-inflammatory cytokines (such as interferon-γ, tumor necrosis factor-α and granulocyte/monocyte colony stimulating factor)." (PMID 38878190, 2024). "First, therapies targeting IL-21/IL-21R are under development for type 1 diabetes, rheumatoid arthritis, and psoriasis, and our findings suggest that therapies blocking IL-21 or IL-21 signaling may be effective as a therapeutic target for inflammatory neuropathies." (PMID 39087473, 2024). "Overproduced cytokines of Th17 cells, especially IL-17A, IL-17F, IL-21, and IL-22, play a role in osteodestructive diseases such as rheumatoid arthritis (RA) and PD." (PMID 36983201, 2023). "Interleukin-21 (IL-21) is a cytokine that plays a crucial role in pathogenesis and activity of the rheumatoid arthritis (RA)." (PMID 31763680, 2020). "Much about IL-21 has been studied in rheumatoid arthritis (RA), and researchers have reported elevated serum and synovial tissues levels of this cytokine in RA as the disease severity increased." (PMID 26998377, 2016). "In rheumatoid arthritis (RA) patients, IL-21 has been found to impair the pro-inflammatory activity of M1-like macrophages in synovial fluid and to inhibit LPS-induced secretion of inflammatory mediators by synovial fluid macrophages, thereby exerting anti-inflammatory effects." (PMID 40376002, 2025). "These cells were first detected in the synovial fluid and tissue of patients with rheumatoid arthritis (RA) patients, and phenotypically resemble Tfh, in particular through the secretion of IL‐21, a central cytokine for B‐cell differentiation and CXCL13, a B‐cell chemoattractant." (PMID 40538220, 2025). "In autoantibody-driven rheumatoid arthritis, TH17 cells regulated the expression of β-galactoside α2,6-sialyltransferase 1 through IL-22 and IL-21, which induced glycan changes in autoantibodies coinciding with the inflammatory phase of arthritis." (PMID 39680460, 2024). "Interleukin-21 (IL-21), produced by stimulated CD4+ T immune cells, plays a significant role in the progression of rheumatoid arthritis (RA) via induction of inflammatory factors and matrix metalloproteinases (MMPs) such as MMP-3 and MMP-13." (PMID 32380783, 2020). "Patients with rheumatoid arthritis, SLE, type 1 diabetes mellitus, and Crohn's disease can participate in phase 1 and 2 clinical trials with anti-IL-21 monoclonal antibody therapy." (PMID 31024571, 2019). "This was followed by the demonstration of elevated expression and/or production of IL-21 in human autoimmune conditions including SLE, rheumatoid arthritis, and Sjogren’s syndrome." (PMID 24600453, 2014). "Furthermore, in rheumatoid arthritis patients with higher disease activity (DAS28 > 5.1) and healthy control levels, IL-21 levels were also comparable." (PMID 33673829, 2021).
rheumatoid arthritis (continued). "As the DAS28 scores represent the disease severity of rheumatoid arthritis patients, we hypothesized a possible correlation between DAS28 scores and plasma levels of IL-21." (PMID 33673829, 2021). "Particular attention is given to the PD-1hi CXCR5− Bcl6low T peripheral helper (Tph) cell population in rheumatoid arthritis, which infiltrates inflamed synovium through expression of chemokine receptors such as CCR2 and augments synovial B cell responses via CXCL13 and IL-21." (PMID 30190721, 2018). "Interleukin-21 (IL-21) is a T-cell-derived cytokine whose receptor is expressed on a variety of cells and therefore might have pleiotropic roles in the pathogenesis of rheumatoid arthritis (RA)." (PMID 27535236, 2016). "Studies have revealed that cytokines such as RORγt, IL-17A, and IL-21 expressed in the mucosa not only contribute to inflammatory bowel disease but also lead to elevated mRNA levels of IL-17A, IL-22, and TNF-α in knee joint tissues, which was observed in mouse models of rheumatoid arthritis." (PMID 41400824, 2026). "Besides, CD4+ IL-21+ cells sorted from the synovial fluid can induce fibroblast-like synovial cells to secrete MMP-1 and MMP-3, which promote inflammation and joint pathological changes in patients with rheumatoid arthritis." (PMID 37628716, 2023). "In addition, in certain inflammatory sites, such as synovium from rheumatoid arthritis patients, non-classic Tfh-like cells have been identified, which are CXCR5low but have high expression levels of Bcl-6, PD-1, and IL-21." (PMID 30410493, 2018). "In rheumatoid arthritis (RA), high protein levels of IL-23 and IL-17F were detected in the synovial fluid of patients displaying ectopic lymphoid follicles, and a positive correlation was observed between CD21L mRNA (as a TLS marker) and IL-23 but also IL-17F, IL-21, and IL-22 mRNAs." (PMID 27752258, 2016). "Th17 related cytokines such as IL-17 and IL-21 are also reported to be enhanced and contribute to inflammatory processes in SLE and other rheumatic diseases such as rheumatoid arthritis (RA) and psoriasis." (PMID 26504851, 2015). "Moreover, EBV-positive Sjögren’s Syndrome patients had higher IL-21-producing T cells compared to controls, and elevated blood EBV DNA levels correlated with increased levels of IL-17A in rheumatoid arthritis patients but not in controls." (PMID 40722611, 2025).